ANAPC5 (anaphase promoting complex subunit 5)
Description:
Component of the anaphase promoting complex/cyclosome (APC/C), a cell cycle-regulated E3 ubiquitin ligase that controls progression through the cell cycle. APC/C acts by mediating ubiquitination and subsequent degradation of target proteins: it mainly mediates the formation of 'Lys-11'-linked polyubiquitin chains and, to a lower extent, the formation of 'Lys-48'- and 'Lys-63'-linked polyubiquitin chains. APC/C catalyzes assembly of branched 'Lys-11'-/'Lys-48'-linked branched ubiquitin chains on target proteins. APC/C is activated by CDC20 in the metaphase/anaphase transition of cell cycle, targeting the degradation of cyclin B and securin. APC/C is regulated by the mitotic checkpoint complex (MCC), which inhibits APC/C and delays chromosome segregation.
Synonyms: APC5
Tractability: PROTAC: ubiquitination databases record sites on it; its protein half-life has been measured.
Gene: Protein-coding gene on chromosome 12 (121,308,245 to 121,399,896, reverse strand). Ensembl gene ENSG00000089053.
Subcellular location: Nucleus; Cytoplasm, cytoskeleton, spindle
Subcellular location (Human Protein Atlas): Nucleoplasm
Pathways (Reactome):
Cell Cycle: APC-Cdc20 mediated degradation of Nek2A; APC/C:Cdc20 mediated degradation of Cyclin B; APC/C:Cdc20 mediated degradation of Securin; APC/C:Cdc20 mediated degradation of mitotic proteins; APC/C:Cdh1 mediated degradation of Cdc20 and other APC/C:Cdh1 targeted proteins in late mitosis/early G1; Autodegradation of Cdh1 by Cdh1:APC/C; Cdc20:Phospho-APC/C mediated degradation of Cyclin A; Conversion from APC/C:Cdc20 to APC/C:Cdh1 in late anaphase; Inactivation of APC/C via direct inhibition of the APC/C complex; Phosphorylation of the APC/C; Regulation of APC/C activators between G1/S and early anaphase; Separation of Sister Chromatids
DNA Replication: Assembly of the pre-replicative complex; CDK-mediated phosphorylation and removal of Cdc6
Cellular responses to stimuli: Senescence-Associated Secretory Phenotype (SASP)
Disease: Aberrant regulation of mitotic exit in cancer due to RB1 defects
Gene expression (Transcription): Transcriptional Regulation by VENTX
Immune System: Antigen processing: Ubiquitination & Proteasome degradation
Gene Ontology:
Molecular function: protein phosphatase binding
Biological process: anaphase-promoting complex-dependent catabolic process; protein branched polyubiquitination; protein K11-linked ubiquitination; protein K48-linked ubiquitination; positive regulation of mitotic metaphase/anaphase transition; regulation of meiotic cell cycle; regulation of mitotic cell cycle; protein ubiquitination
Cellular component: anaphase-promoting complex; nucleus; spindle; cytosol; nucleoplasm
Genetic constraint (gnomAD): Loss-of-function variants: 51 observed, 72.44 expected, observed/expected ratio (o/e) 0.7, 90% interval 0.56 to 0.89. The upper end of that interval is the gene's LOEUF score, 0.89, which puts it in group 3 of 6, group 1 being the genes least tolerant of losing a copy. Missense variants: 603 observed, 870.04 expected, observed/expected ratio (o/e) 0.69, 90% interval 0.65 to 0.74. Synonymous variants: 313 observed, 346.27 expected, observed/expected ratio (o/e) 0.9, 90% interval 0.82 to 0.99.
Homologues: Orthologues: chimpanzee ANAPC5 (100% identical), macaque ANAPC5 (100% identical), dog ANAPC5 (98% identical), pig ANAPC5 (97% identical), rabbit ANAPC5 (97% identical), guinea pig ANAPC5 (95% identical), rat Anapc5 (93% identical), mouse Anapc5 (93% identical), tropical clawed frog anapc5 (82% identical), zebrafish anapc5 (61% identical), Drosophila melanogaster ida (26% identical), Caenorhabditis elegans such-1 (18% identical), and 1 more.
Diseases named in the same sentence as ANAPC5 in open-access papers:
ANAPC5 is named in the same sentence as 8 diseases in open-access papers, as found by Europe PMC text mining. Sharing a sentence is not in itself a finding about the gene and the disease. The quoted sentences say what the papers report.
cancer (7 papers, 2011 to 2025). A tumor composed of atypical neoplastic, often pleomorphic cells that invade other tissues. "Only 6 CDGs appeared under cell cycle and those were ANAPC13, ANAPC5, MAD2L2, GADD45G, CCND2, and surprisingly MYC — a gene often implicated as a cancer driver." (PMID 39774001, 2025). "These include the tumour suppressors, PDCD4, RB1, STK2, transcriptional regulators with reported roles in cancer, BCL9L, STAT5B and proteins that are involved in control of the cell cycle, ANAPC4, ANAPC5, RBX1." (PMID 35573784, 2022). "The third group contains four mitotic proteins (ANAPC5, CDC16, CDC20, CDC27) and shRNAs targeting these mitotic genes are predicted to sensitize cancer cells to GSK461364A." (PMID 22248814, 2011).
tumor (5 papers, 2017 to 2022). "ANAPC5 was overexpressed in NSCLC tumor B cells and PBL T cells and was associated with resistance to cisplatin in NSCLC epithelial cells." (PMID 35804895, 2022). "Exonic deletions were detected in the PPP2R5A, FHIT, LRP1B, and OPCML tumor suppressor genes, as well as in genes implicated in cellular proliferation (CCNB1, ANAPC5, PIK3C2A) and DNA repair (SMARCA5)." (PMID 30836646, 2019).
ANAPC5 also shares sentences with these, for which no sentence is quoted: HCMV infection (2 papers); viral infection (2); genochondromatosis (1); infection (1); Infertility (1); lung carcinoma (1).